TBX3 (T-box transcription factor 3)
Diseases named in the same sentence as TBX3 in open-access papers (continued):
Sharing a sentence is not in itself a finding about the gene and the disease.
tumor (continued). "Molecularly, ZFHX3 could bind to the promoters of MYC and TBX3 to activate their transcription, which could then partially mediate ZFHX3′s effects on cell proliferation and tumor growth." (PMID 33217982, 2020). "Large tumor modules were observed in all the test mice that received implanted cells that ectopically expressed wild-type Tbx3 (7 out of 7 mice), while no tumor nodules were observed in the control group." (PMID 30151243, 2018). "The Tbx3 and E-cadherin mRNA expression ratios in the tumor (T) and non-tumor (N) tissues were calculated." (PMID 30151243, 2018). "The ability of TBX3 to drive non-tumourigenic cells to form tumours is shown to be highly sensitive and specific (100% in both cases)." (PMID 24098938, 2013). "Although over-expression of TBX3, alone, did not induce tumor formation it did promote accelerated mammary gland development by increasing mammary epithelial cell proliferation." (PMID 22039763, 2011). "Therefore, pathologically activated BRAF/MAPK signaling, possibly by BRAFV600E, initiates and promotes tumor development through transcriptionally elevating USP15 and protecting TBX3 from degradation, in addition to direct transcriptionally up-regulating TBX315." (PMID 38750011, 2024). "The HMLE-TBX3-overexpressing cells were also injected into the mammary fat pads of nude mice, but no tumors were observed, suggesting elevated levels of TBX3 alone is not enough to promote tumor development from these cells." (PMID 31910858, 2020). "It is not thus surprising that the transcription factor Tbx3, being involved in tumour progression, could control the GATA3 transcription factor." (PMID 19828084, 2009). "Together, these results strongly suggest that TBX3 does not appear to confer oncogenic properties in RMS cells and appears instead to function as a tumor suppressor by repressing TBX2." (PMID 30979887, 2019). "In contrast, high expression of TBX3 in tumor cells (CK19+) showed non-inflammatory phenotypes, and extensive expression of TBX3 in tumor cells resulted in a large accumulation of CAFs and inhibited CD8+ T cell infiltration in the tumor area." (PMID 39897553, 2025). "Although MYC and TBX3 could partially mediate ZFHX3′s promoting effects on cell proliferation and tumor growth, direct evidence is still lacking at this time because findings from the rescue experiments were not conclusive." (PMID 33217982, 2020).
cardiac diseases (2 papers, 2019 to 2025). "Among 244 genes associated with cardiac diseases, three candidate variants with high confidence of pathogenicity were identified in the UTRs of SCO2, CALM2 and TBX3 based on a rigorous filtering strategy." (PMID 39266800, 2025).
infection (2 papers, 2018 to 2023). The state of being infected such as from the introduction of a foreign agent such as serum, vaccine, antigenic substance or organism. "We found that infection with Jad/C(4fC) resulted in the significant upregulation of c-MYC (P < 4 × 10−6), TBX3 (P < 0.0006), AXIN2 (P < 0.0068), FNDC3B (P < 1 × 10−5), FASN (P < 0.0005) and CCND1 (P < 0.0002), with c-MYC and TBX3 showing the highest upregulation levels." (PMID 30046100, 2018).
adenocarcinoma (1 paper, 2025). A common cancer characterized by the presence of malignant glandular cells. "However, no significantcorrelation was found between HOXB13 and TBX3 transcriptionlevels and the overall survival of patients diagnosed withprostate adenocarcinoma." (PMID 41164275, 2025).
cardiovascular diseases (1 paper, 2021). "Expression of hsa-mir-663a and TBX3 were consistent in cardiovascular diseases, but these genes might be novel target for GDM." (PMID 33890634, 2021).
prostate (1 paper, 2025). "High-throughput sequencing methods such as single-cell RNA-seq have enabled deep characterization of the prostate BCC genome, revealing key driver mutations of CASC5, NUTM1, PTPRC, KMT2C, and TBX3, genes also involved in chromatin remodeling and stem cell regulation." (PMID 40124187, 2025).
TBX3 also shares sentences with these, for which no sentence is quoted: atrial septal defect (2 papers); cholangiocarcinoma (2); endometriosis (2); Hypertension (2); hypertrophic cardiomyopathy (2); small cell lung carcinoma (2); synovial sarcoma (2); anaplastic thyroid carcinoma (1); aortic stenosis (1); asthma (1); basal cell carcinoma (1); bladder tumours (1); bone sarcoma (1); Brugada syndrome (1); childhood cancer (1); clear cell renal cell carcinomas (1); connective tissue tumors (1); dilated cardiomyopathy (1); dwarfism (1); embryonal rhabdomyosarcoma (1); endometrial cancer (1); epithelioid sarcoma (1); esophageal carcinoma (1); Ewing sarcoma (1); familial breast cancer (1); fatty liver disease (1); fibrosis (1); genetic disorder (1); Glucose intolerance (1); hematopoietic neoplasms (1).
A further 24 diseases each share a sentence with TBX3 in 1 paper.